EXT2 (exostosin glycosyltransferase 2)
Description:
Glycosyltransferase forming with EXT1 the heterodimeric heparan sulfate polymerase which catalyzes the elongation of the heparan sulfate glycan backbone. Glycan backbone extension consists in the alternating transfer of (1->4)-beta-D-GlcA and (1->4)-alpha-D-GlcNAc residues from their respective UDP-sugar donors. Both EXT1 and EXT2 are required for the full activity of the polymerase since EXT1 bears the N-acetylglucosaminyl-proteoglycan 4-beta-glucuronosyltransferase activity within the complex while EXT2 carries the glucuronosyl-N-acetylglucosaminyl-proteoglycan 4-alpha-N-acetylglucosaminyltransferase activity. Heparan sulfate proteoglycans are ubiquitous components of the extracellular matrix and play an important role in tissue homeostasis and signaling.
Synonyms: SOTV; SSMS
Tractability: Small molecule: a structure with a bound ligand is known. Antibody: UniProt places it where antibodies can reach, with medium confidence; UniProt predicts a signal peptide or a membrane-spanning region; its Gene Ontology location is reachable by antibodies, with medium confidence. PROTAC: ubiquitination databases record sites on it.
Gene: Protein-coding gene on chromosome 11 (44,095,648 to 44,251,962, forward strand). Ensembl gene ENSG00000151348.
Subcellular location: Golgi apparatus membrane; Golgi apparatus, cis-Golgi network membrane; Endoplasmic reticulum membrane; Secreted
Subcellular location (Human Protein Atlas): Golgi apparatus
Pathways (Reactome):
Disease: Defective EXT1 causes exostoses 1, TRPS2 and CHDS; Defective EXT2 causes exostoses 2
Metabolism: HS-GAG biosynthesis
Gene Ontology:
Molecular function: acetylglucosaminyltransferase activity; glucuronosyl-N-acetylglucosaminyl-proteoglycan 4-alpha-N-acetylglucosaminyltransferase activity; glucuronosyltransferase activity; glycosyltransferase activity; N-acetylglucosaminyl-proteoglycan 4-beta-glucuronosyltransferase activity; protein binding; protein heterodimerization activity; protein homodimerization activity; heparan sulfate N-acetylglucosaminyltransferase activity
Biological process: glycosaminoglycan biosynthetic process; heparan sulfate proteoglycan biosynthetic process; ossification; polysaccharide biosynthetic process; glycoprotein biosynthetic process
Cellular component: catalytic complex; endoplasmic reticulum; endoplasmic reticulum membrane; extracellular exosome; Golgi apparatus; Golgi membrane; membrane; UDP-N-acetylglucosamine transferase complex; extracellular region
Genetic constraint (gnomAD): Loss-of-function variants: 53 observed, 85.95 expected, observed/expected ratio (o/e) 0.62, 90% interval 0.49 to 0.77. The upper end of that interval is the gene's LOEUF score, 0.77, which puts it in group 3 of 6, group 1 being the genes least tolerant of losing a copy. Missense variants: 774 observed, 960.11 expected, observed/expected ratio (o/e) 0.81, 90% interval 0.76 to 0.86. Synonymous variants: 320 observed, 360.08 expected, observed/expected ratio (o/e) 0.89, 90% interval 0.81 to 0.98.
Gene-disease validity (ClinGen):
ClinGen rates the evidence that EXT2 causes each of these diseases.
exostoses, multiple, type 2 (autosomal dominant): Definitive.
Homologues: Orthologues: chimpanzee EXT2 (99% identical), macaque EXT2 (99% identical), dog ACCS (97% identical), rabbit EXT2 (96% identical), mouse Ext2 (95% identical), rat Ext2 (95% identical), guinea pig EXT2 (93% identical), tropical clawed frog ext2 (86% identical), zebrafish ext2 (85% identical), Drosophila melanogaster sotv (48% identical). Paralogues in human: EXTL3 (36% identical), EXT1 (34% identical), EXTL1 (27% identical), EXTL2 (14% identical).
Diseases named in the same sentence as EXT2 in open-access papers:
EXT2 is named in the same sentence as 92 diseases in open-access papers, as found by Europe PMC text mining. Sharing a sentence is not in itself a finding about the gene and the disease. The quoted sentences say what the papers report.
Osteochondroma (30 papers, 2008 to 2025). A common, benign cartiliginous neoplasm arising from the metaphysis of bone. "A mutation in EXT2, a gene known to be involved in osteochondroma development, was identified in OICI-CS-1077 ODX 33,34." (PMID 41419593, 2025). "Patients with EXT1 mutations often exhibit more severe phenotypes, including a higher number of osteochondromas, greater limb deformity, and a higher risk of malignant transformation compared to those with EXT2 mutations." (PMID 39057136, 2024). "Hereditary Multiple Exostoses (HME) is a rare autosomal disorder characterized by the presence of multiple exostoses (osteochondromas) caused by a heterozygous loss of function mutation in EXT1 or EXT2; genes involved in heparan sulfate (HS) chain elongation." (PMID 34815940, 2021). "Decreased levels of HS due to mutations in EXT1 or EXT2 also lead to a skeletal abnormality resulting in one of the most common benign bone tumours in young adults – osteochondroma." (PMID 24628984, 2014). "Previously, we have used zebrafish which harbour mutations in ext2 as a model for MO and shown that ext2−/− fish have skeletal defects that resemble those seen in osteochondromas." (PMID 22253766, 2012). "MO is known as a genetic syndrome manifesting by the formation of multiple osteochondromas caused by the inactivation of EXT1 or EXT2." (PMID 22253766, 2012). "EXT1 and EXT2 variants in the 22 Chinese families with multiple osteochondromas." (PMID 33414810, 2020). "Mutations in exostosin-2 (EXT2) often cause multiple osteochondromas." (PMID 33029143, 2020). "While mosaic mutations and deletions of EXT1 and EXT2 have been reported in the context of multiple osteochondromas, to our knowledge, this is the first time that transcriptomics technologies have been used to diagnose a patient via fusion transcript analysis in the congenital disease setting." (PMID 30632316, 2019). "Current research indicates that mutations in the EXT1 and EXT2 tumor suppressor genes from the EXT gene family are responsible for both sporadic and syndromic osteochondromas, including hereditary multiple exostoses (HME)." (PMID 40034594, 2025). "No significant change in uACR was observed in Ext1(ECKO), consistent with data from multiple osteochondroma (MO) patients, an autosomal dominant disease resulting from loss of function in EXT1 or EXT2." (PMID 38302978, 2024). "The variability in the clinical presentation of HME, such as the number and size of osteochondromas, can be attributed to the different mutations within the EXT1 and EXT2 genes." (PMID 39057136, 2024). "This patient suffered from multiple osteochondromas, an autosomal dominant disease caused by mono-allelic germline mutations in the EXT1 or EXT2 gene." (PMID 35103870, 2022). "Many studies have shown that the etiology of osteochondroma is largely due to genomic mutations in EXT1 and EXT2, resulting in the loss or insufficient synthesis of glycosyltransferases which are related to HS synthesis." (PMID 36360300, 2022). "Loss-of-function mutations in EXT1 and EXT2, the enzymes responsible for HS synthesis, cause HME, an autosomal dominant disorder that is characterized by osteochondromas." (PMID 34890641, 2022). "Mutations in EXT1 or EXT2 result in hereditary multiple exostoses (HME) in humans, a disease that causes the formation of benign bone tumors (osteochondromas) that are associated with GPs." (PMID 36561564, 2022). "Genetic variants of these genes cause multiple exostoses, osteochondromatosis, or EXT1/EXT2-CDG, which are autosomal dominant O-linked glycosylation disorders characterized by the formation of multiple cartilage-capped tumors (osteochondromas)." (PMID 35955863, 2022). "Compound heterozygous Ext1+/−; Ext2+/− deletion mice and conditional Ext1 knockout mice display multiple osteochondromas and closely resemble human HME." (PMID 33632255, 2021).
Osteochondroma (continued). "Multiple osteochondroma (MO) is an autosomal dominant skeletal disorder characterized by the formation of multiple osteochondromas, and exostosin-1 (EXT1) and exostosin-2 (EXT2) are major causative genes in MO." (PMID 26961984, 2016). "Our data on EXT1 and EXT2 from case 2 are in agreement with previously reported expression data from osteochondromas in that they showed low expression levels." (PMID 26043835, 2015). "Several mice models have been developed to study the role of EXT1 or EXT2 in bone and osteochondroma formation." (PMID 24628984, 2014). "Osteochondromas may also be associated with multiple hereditary exostoses linked to mutations in the EXT1 and EXT2 genes." (PMID 41220449, 2025). "In MO pathogenesis, germline heterozygous mutations in EXT1 or EXT2 are not sufficient to cause osteochondroma formation." (PMID 35103870, 2022). "Further clinical testing to determine the cause of the patient's multiple osteochondromas was unrevealing despite extensive profiling of the most likely causative genes, EXT1 and EXT2, including mutation screening by direct sequence analysis and multiplex ligation‐dependent probe amplification." (PMID 30632316, 2019). "Additionally, this EXT2 alteration is classified as deleterious by SIFT, as it is probably damaging with a score of 0.99 by PolyPhen-2, and reported as likely benign for its association with osteochondroma in ClinVar." (PMID 36673024, 2023). "However, Ext2+/− mice do have osteochondroma-like outgrowths on their ribs." (PMID 18654627, 2008). "A search for all Dutch patients registered with both osteochondroma and kidney biopsy (n = 39) showed that an EXT1 or EXT2 mutation does not necessarily lead to specific glomerular morphological phenotypic changes." (PMID 35103870, 2022). "The finding in a subset of osteochondromas of cytogenetic aberrations, mainly 8q deletions, as well as biallelic inactivation of the EXT1 (located in 8q24) or EXT2 (located in 11p11) gene in cells of the cartilage cap supports a neoplastic nature of the tumors." (PMID 26043835, 2015). "In a reciprocal manner, LDN-193189 could be more effective if given prior to osteochondroma initiation or even chronically and if it were to be tested in less aggressive HME mouse models, such as single Ext1+/- or double heterozygous Ext1+/-;Ext2+/- mice." (PMID 28445472, 2017).
Multiple osteochondromas (21 papers, 2011 to 2025). Multiple osteochondromas (MO) is characterised by development of two or more cartilage capped bony outgrowths (osteochondromas) of the long bones. "Heterozygous loss-of-function variants in the EXT1 and EXT2 genes are the primary cause of hereditary multiple osteochondromas and are identified in the majority of reported cases." (PMID 41282553, 2025). "In multiple osteochondromas, EXT2 is considered as a tumor suppressor gene, with mutations leading to exostoses development." (PMID 40234611, 2025). "A large number of studies have found that mutations in EXT1 and EXT2 lead to loss of the protein domain, which is closely related to multiple osteochondromas." (PMID 35899200, 2022). "Clinical data and mutations identified in EXT1 and EXT2 in 6 Chinese probands with hereditary multiple exostoses." (PMID 31096510, 2019). "ACCS:EXT2 (#9) - EXT2 is a tumour supressor gene implicated in multiple osteochondroma, with the gene being affected by a wide-range of mutations including frameshift and splice-site mutations." (PMID 22761941, 2012). "Mutations in EXT2 have been also reported in patients with multiple osteochondromas." (PMID 25050621, 2014). "Multiple osteochondromas (MO; OMIM #133700, #133701), is a rare condition caused by mutations on the exostosin-1 (EXT1) or exostosin-2 (EXT2) gene in 90% of patients." (PMID 33917765, 2021). "For example, in EXT2, germline variants (NP_000392.3:p.Trp79* and NP_997005.1:p.Trp46*) are associated with hereditary multiple osteochondromas, a non-cancerous condition that can develop into chondrosarcoma." (PMID 37461096, 2023). "There are no data about EXT1 and EXT2 pathogenic variants in patients with multiple osteochondromas in Brazilian population." (PMID 29529714, 2018). "Multiple osteochondromas (also called hereditary multiple exostoses) is an autosomal dominant disorder characterized by multiple cartilaginous tumors, which are caused by mutations in the genes for exostosin-1 (EXT1) and exostosin-2 (EXT2)." (PMID 26839764, 2016). "Multiple osteochondromas (MO), previously known as hereditary multiple exostosis (HME), is a genetic dominant syndrome occurring at the frequency of 1∶50,000 that is caused by mutation of one of the two EXOSTOSIN (EXT) genes, EXT1 or EXT2." (PMID 22253766, 2012). "Patients may develop solitary osteochondromas due to injuries at the metaphysis or multiple osteochondromas associated with mutations in the Exostosin 1 (EXT1) and 2 (EXT2) genes, a condition known as hereditary multiple osteochondromas (HMO; previously called hereditary multiple exostoses, HME)." (PMID 39062860, 2024). "Hereditary Multiple Exostoses (HME), also known as Multiple Osteochondromas (MO) is a rare genetic disorder characterized by multiple benign cartilaginous bone tumors, which are caused by mutations in the genes for exostosin glycosyltransferase 1 (EXT1) and exostosin glycosyltransferase 2 (EXT2)." (PMID 33632255, 2021).
hereditary multiple exostoses (17 papers, 2013 to 2025). An exostosis that has_material_basis_in a mutation on the genes EXT1, EXT2 and EXT3 which results_in multiple bony spurs throughout a child's growth. "Hereditary Multiple Exostoses (HME) is a rare pediatric disorder caused by loss-of-function mutations in the genes encoding the heparan sulfate (HS)-synthesizing enzymes EXT1 or EXT2." (PMID 28445472, 2017). "EXT1 and EXT2 are tumor suppressors, associated with hereditary multiple exostoses, characterized by the development of benign skeletal tumors in patients." (PMID 26482785, 2015). "The EXT2 gene is causative of hereditary multiple exostoses (HME)." (PMID 34567566, 2021). "We hypothesized that loss of function of EXT1 or EXT2 in subjects with hereditary multiple exostoses (HME) affects pancreatic insulin secretion capacity and development." (PMID 25541963, 2014). "However, although mutations in either EXT1 or EXT2 can result in development of Hereditary Multiple Exostoses, mutations in EXT1 are associated with a higher disease burden." (PMID 25541963, 2014). "Hereditary multiple exostoses is an autosomal dominant disorder, caused by pathogenic variants in EXT1 or EXT2 in 70–95% of cases, with EXT1 affected twice as frequently as EXT2." (PMID 31577830, 2019). "EXT1 or EXT2 loss of function mutations results in the autosomal dominant disease multiple osteochondromas (MO, OMIM No. 133700 and 133,701), previously also known as hereditary multiple exostoses (HME) and multiple hereditary multiple exostoses (MHE)." (PMID 35103870, 2022).
autoimmune disease (8 papers, 2021 to 2025). A disorder resulting from loss of function or tissue destruction of an organ or multiple organs, arising from humoral or cellular immune responses of the individual to their own tissue constituents. "In our study, 60% of the samples (3 of 5 cases) from patients with lupus class V showed positive staining of Ext1/Ext2, supporting that they are associated with autoimmune diseases." (PMID 35194125, 2022). "Such important biomarkers include anti-PLA2R and anti-THSD7A antibodies, which are specific to the primary form, as well as exostosin (EXT-1 and EXT-2), as markers of membranous nephropathy secondary to autoimmune diseases, particularly LN." (PMID 39682589, 2024). "Most patients (85%) with EXT1/EXT2-positive MN had other autoimmune diseases including lupus (8/26), revealing EXT1 and EXT2 as potential target antigens for SMN." (PMID 33808418, 2021). "EXT1 and EXT2 are the primary antigens for a subset of autoimmune diseases, including lupus." (PMID 37048133, 2023). "Notably, MN associated with EXT1/EXT2 and NELL1-related malignant tumors may be linked to autoimmune diseases, such as systemic lupus erythematosus and mixed connective tissue disease." (PMID 40852718, 2025).
chondrosarcoma (8 papers, 2011 to 2025). A malignant cartilaginous matrix-producing mesenchymal neoplasm arising from the bone and soft tissue. "The heterozygous loss and homozygous deletion of exostosin 1/2 (EXT1/EXT2) genes have been reported in peripheral chondrosarcomas." (PMID 38275833, 2024). "Overall, mutations in IDH1/IDH2 or EXT1/EXT2 have been shown to have a role in the pathogenesis of most common central or peripheral chondrosarcomas, respectively." (PMID 32295254, 2020). "Nevertheless, the loss of heterozygosity in the EXT1 and EXT2 genes has been implicated to cause hereditary multiple exostoses, one of the most common inherited musculoskeletal conditions, with an incidence of 1 in 50,000, whose most serious complication is chondrosarcoma transformation." (PMID 32295254, 2020). "Previous findings suggested that EXT1, EXT2, and Sox9 can be considered genetic markers in the diagnosis and prognosis of chondrosarcoma." (PMID 35760773, 2022). "Rarely, persons with multiple hereditary exostoses (EXT1, MIM 608177; EXT2, MIM 608210)—both genes encode glycosyltransferases involved in heparan sulfate production—may also develop chondrosarcomas later in life." (PMID 39941818, 2025). "Genetically, two main groups of chondrosarcomas exist: central chondrosarcomas, characterized by mutations in the isocitrate dehydrogenase genes IDH1 and IDH2, and secondary peripheral chondrosarcomas, characterized by alterations in the exostosin glycosyltransferase 1 (EXT1) and 2 (EXT2) genes." (PMID 32295254, 2020). "In chondrosarcoma tissues, the expression of EXT1 and EXT2 usually has a significant reduction, whereas SOX9 has a higher expression." (PMID 35760773, 2022). "Additionally, we found expression of genes such as Collagen, type I, alpha 1 (COL1A1), Exostoses (multiple) 1 (EST1), Exostoses (multiple) 2 (EXT2), Vimentin (VIM), and Osteoprotegerin (TNFRSF11B), which are known to be involved in development of conventional chondrosarcomas." (PMID 22448124, 2012).
membranous nephropathy (8 papers, 2022 to 2026). "In this context, the exostosin 1 (EXT1)/exostosin 2 (EXT2) heterodimer has emerged as a novel antigen in membranous nephropathy associated with SLE." (PMID 42279461, 2026). "Both EXT1/EXT2 and NCAM1 are associated with subepithelial immune deposits, suggesting mechanisms of injury in MLN that are different from other forms of membranous nephropathy." (PMID 41440943, 2025). "A subset of potential antigens, including exostosin 1 (EXT1) and EXT2, as well as neural cell adhesion molecule 1 (NCAM1), has been identified as candidates in secondary membranous nephropathy associated with autoimmune diseases, including MLN." (PMID 41440943, 2025).